SMARCA4 (SWI/SNF related BAF chromatin remodeling complex subunit ATPase 4)
Diseases named in the same sentence as SMARCA4 in open-access papers (continued):
Sharing a sentence is not in itself a finding about the gene and the disease.
lung adenocarcinoma (54 papers, 2014 to 2026). A carcinoma that arises from the lung and is characterized by the presence of malignant glandular epithelial cells. "The authors concluded that the loss of either or both SMARCA2 and SMARCA4 led to the progression of lung adenocarcinoma into a solid-predominant tumor and to epithelial–mesenchymal transition, with loss of the bronchial epithelial phenotype." (PMID 39888726, 2025). "In the present study, loss of SMARCA4 was only found in 2.5% (6/241) of the lung adenocarcinoma samples." (PMID 38710944, 2025). "In vivo, combined treatment with intermittent ATRi and continuous PARPi showed greater inhibition of tumor growth than ATRi alone in SMARCA4-deficient lung adenocarcinoma xenograft models." (PMID 39875375, 2025). "We previously reported that loss of SMARCA4 in lung adenocarcinomas led to increased NRF2 signaling, including expression of the NRF2 targets HMOX1 and GSTM4." (PMID 38358974, 2024). "As an example, SMARCA4 loss accelerates tumor progression and promotes lung adenocarcinoma (LUAD) dedifferentiation, while abrogation of another key SWI/SNF component, Arid1a, suppresses tumor initiation and metastasis in hepatocellular carcinoma." (PMID 39080761, 2024). "SMARCA4-dNSCLC exhibits the differentiation of epithelial architecture, and the focal glandular formation can be observed in a few SMARCA4-deficient lung adenocarcinomas." (PMID 38374950, 2024). "Out of genes relevant to lung adenocarcinoma, any alterations in SMARCA4 were associated with shortened OS (HR 2.732, 95%CI 1.291-5.782, P=0.009) and DSS (HR 2.901, 95%CI 1.213-6.939, P=0.017) in univariable analysis." (PMID 35964518, 2022). "The majority of the reports evaluating the histopathology of SMARCA4 altered lung adenocarcinomas have concentrated in tumors with loss of immunohistochemical BRG1 expression and, presumably truncating SMARCA4 variants." (PMID 35964518, 2022). "It is important for SMARCA4 to be intact in oncogene-driven lung adenocarcinomas, as loss of SMARCA4 dampens the KRAS signaling in a KRAS-addicted cancer and, subsequently, impairs proliferation of the tumor cells." (PMID 34440689, 2021). "Distinguishing this pathogenesis supports that treatment should be aimed directly towards the SWI/SNF complexes in lung adenocarcinomas and other malignancies related to SMARCA4 mutation." (PMID 34440689, 2021). "The constant evolution of molecular genotyping, which is used for the management of lung adenocarcinomas, has led to the current focus on tumor suppressor genes, specifically the loss of function mutation in the SMARCA4 gene." (PMID 34440689, 2021). "Mutations of SMARCA4 represent a genetic factor leading to adverse clinical outcome in lung adenocarcinoma." (PMID 34675941, 2021). "Studies identified nine SMARCA4 mutations widely distributed along the SMARCA4 gene, which includes Glu1023* and Glu1346del mutations, as well as a common missense mutation G1232S/V in lung adenocarcinoma patients." (PMID 34440689, 2021). "Lung adenocarcinoma (LADC) patients frequently harbor mutations in SMARCA4, a core component of this multisubunit complex." (PMID 34316685, 2020). "Lung adenocarcinomas harbouring SMARCA4 mutations, including missense mutations, had lower levels of SMARCA4 transcripts (P<0.01)." (PMID 28102363, 2017). "In the case of mutations of SMARCA4 in lung adenocarcinomas (LUAD), the top ranking oncomodules include SOX-9 and transcription factors of the HSF family, which have been linked to tumorigenesis before." (PMID 27095575, 2016). "FBN2 disruption precedes the subclonal deletion of genes along chromosome 9p, including significantly mutated known lung adenocarcinoma genes SMARCA4, KEAP1, and STK11." (PMID 25160065, 2014).
lung adenocarcinoma (continued). "(n=89), and multiplexed immunohistochemistry (IHC) staining of these two cases to decipher the poor prognosis dependent on the immunosuppressive barrier formed by FAP+ fibroblasts and SPP1+ macrophages in the SMARCA2-deficient while SMARCA4-preserved poorly differentiated lung adenocarcinoma (LUAD)." (PMID 40453096, 2025). "Notably, the biopsy history indicated right lung adenocarcinoma, suggesting poorly differentiated cancer with dedifferentiation (SMARCA4-deficient) and the presence of an EGFR E19del mutation." (PMID 41142791, 2025). "Additionally, constitutive loss of SMARCA4 in lung adenocarcinoma (LUAD) cells leads to heterochromatin formation." (PMID 39875375, 2025). "SMARCA4 has a high mutation frequency in lung adenocarcinoma (LUAD) and its mutation might lead to low gene expression." (PMID 39322625, 2024). "SMARCA4 has been shown to be significantly mutated in lung adenocarcinomas and esophageal cancer." (PMID 29522538, 2018). "HNF4α-positive cases among 241 lung adenocarcinomas were stratified based on TTF-1 and SMARCA4 expressions, histological subtypes, and driver mutations." (PMID 38710944, 2025). "In 1817 KRAS-mutant lung adenocarcinomas, KEAP1 and SMARCA4 mutations correlated with metastasis and poor survival, while STK11’s impact varied by metastatic site and KEAP1 status." (PMID 40758706, 2025). "Immunohistochemical analysis of 93 primary lung adenocarcinomas revealed loss of SMARCA2 and SMARCA4 in 17% and 12% of cases, respectively." (PMID 39888726, 2025). "For the lung adenocarcinoma (LUAD) patients, the mutational rate in DACH1 was higher in the higher-score individuals, while CDKN2A and SMARCA4 were higher in the lower-score individuals." (PMID 41431699, 2025). "Mutations in STK11 and KEAP1 are associated with resistance to ICI treatment in lung adenocarcinoma, but these mutations are difficult to sufficiently predict the efficacy of ICI treatment in SMARCA4-UT." (PMID 39497014, 2024). "We previously reported that loss of the catalytic subunits of SWI/SNF (SMARCA4 and SMARCA2) in lung adenocarcinoma tumors and lung cancer cell models altered KEAP1-NRF2 signaling." (PMID 38358974, 2024). "Increasingly, novel genes such as SMARCA1, SMARCA4 and SMAD4 alterations in lung adenocarcinoma are independently associated with LNM in lung adenocarcinoma." (PMID 39720561, 2024). "Furthermore, loss of SMARCA4 in lung adenocarcinoma resulted in the acquisition of highly de-differentiated cancer cell traits and increased metastatic incidence, suggesting that the involvement of SMARCA4 in regulating cancer stemness might be associated with the cell of origin." (PMID 36674511, 2023). "Our case report describes a 73-year-old man who was diagnosed with SMARCA4-mutant advanced lung adenocarcinoma." (PMID 37214462, 2023). "We additionally interrogated lung adenocarcinoma (LUAD) samples, where BRG1 (SMARCA4) is more commonly mutated." (PMID 35365638, 2022). "Findings show that KRAS-independent lung adenocarcinomas harbor higher rates of SMARCA4 inactivation as compared to KRAS-addicted lung adenocarcinomas." (PMID 34440689, 2021). "We and others found that SMARCA4 (SWI/SNF-related, matrix-associated, actin-dependent regulator of chromatin, subfamily A, member 4) mutations were present in 7–8% of lung adenocarcinoma (LADC) patients." (PMID 34316685, 2020). "High expression of SMARCA4 was significantly associated (COX P ≤ 0.01) with a poor prognosis in breast and ovarian cancer, lung adenocarcinoma, liposarcoma and uveal melanoma datasets." (PMID 29391527, 2018).
lung adenocarcinoma (continued). "In TCGA lung adenocarcinoma data sets there was a small, statistically significant increase in HURP, AURKA, TPX2 or RAN mRNA levels correlating with SMARCA4 mutations of all types." (PMID 28102363, 2017). "HNF4α expression and SMARCA4 loss were thought to be features of non-terminal respiratory unit (TRU)-type lung adenocarcinomas, but their relationships remained unclear." (PMID 38710944, 2025). "Lung adenocarcinoma cases with altered SMARCA4 showed a poorer prognosis." (PMID 34675941, 2021). "SMARCA4 gene mutation is reported to encompass 12% of non-oncogenic addicted lung adenocarcinomas and 5% are co-altered among oncogenic-driven lung adenocarcinomas." (PMID 34440689, 2021). "This is possible when the SMARCA4 in a KRAS-dependent lung adenocarcinoma is a missense mutation, identified through an intact BRG1 expression or the loss of BRG1 expression caused by a nonsense, frameshift, or splice site mutation in the SMARCA4 gene in a KRAS-independent lung adenocarcinoma." (PMID 34440689, 2021). "Finally we show that SMARCA4 proficient lung adenocarcinoma have higher AKT and mTOR activation." (PMID 40069402, 2025). "Furthermore, because of the recent description of SMARCA4 deficient tumors, the therapy is not as well-known compared with lung adenocarcinoma." (PMID 35885495, 2022). "Therefore, mutations of SMARCA4 represent a genetic factor leading to adverse clinical outcome in lung adenocarcinoma treated by either nonimmunotherapy or immunotherapy." (PMID 33107184, 2021). "Although SMARCA4 is frequently inactivated in lung adenocarcinoma (LUAD), a subset of tumors exhibits elevated SMARCA4 expression, suggesting a context-dependent oncogenic function." (PMID 42010258, 2026). "In one study which used a lung adenocarcinoma model, the SWI/SNF ATPase SMARCA4 (BRG1) was found to be a tumor suppressor, largely due to its impact on glucose metabolism." (PMID 38666605, 2024). "70-90% of SMARCA4 alterations were homozygous in NSCLC subtypes including the most common subtype, lung adenocarcinoma, with 15-40% representing truncating alterations." (PMID 33144586, 2020). "Also, CCC does not show the polyphenotypic immunohistochemical expression typical of SSCOHT, but is, instead, positive for Napsin A. Among non-ovarian solid tumors, inactivating mutations of SMARCA4 have been rarely described in lung adenocarcinomas, and were associated with a poor outcome." (PMID 32149361, 2020). "In keeping with our in vitro findings, we observed a mild but significant correlation (r = 0.33; p = 0.002) between SMARCA4 and CCND1 mRNA expression in a cohort of 83 lung adenocarcinomas (LUADs), a main NSCLC subtype." (PMID 30718506, 2019). "The markers CKpan, P40, P63, Claudin4, CK5/6, CK7, NUT, and NapsinA effectively ruled out lung adenocarcinoma, squamous cell carcinoma, NUT carcinoma and Thoracic SMARCA4-deficient undifferentiated tumor (SMARCA4-UT)." (PMID 40661782, 2025). "All the available tested thoracic SMARCA4-UT samples were negative for lung adenocarcinoma markers (CK7, TTF-1, and Napsin A) and for squamous cell carcinoma markers (p63, p40, and CK5&6)." (PMID 38374950, 2024). "The uniform lack of actionable gene alterations of conventional lung adenocarcinomas; namely, EGFR mutation, EML4-ALK rearrangement, and ROS1 rearrangement are common knowledge with regards to the SMARCA4-dNSCLC tumors." (PMID 34440689, 2021). "In addition, SMARCA4 is positively correlated with expression of multiple immune checkpoint genes, and SMARCA4 expression is related to high TMB in some cancer types, such as lung adenocarcinoma." (PMID 34675941, 2021).
lung adenocarcinoma (continued). "Unlike SMARCA4‐dNSCLC, classical lung adenocarcinomas are mostly TTF‐1 positive expression and HepPar‐1 negative expression, SMARCA4‐UTs are usually positive for stem cell markers and negative for epithelial markers." (PMID 37184108, 2023).
prostate carcinoma (49 papers, 2011 to 2026). A carcinoma that arises from epithelial cells of the prostate gland. "In most cancers, including breast, colorectal, and prostate cancers, SMARCA4 upregulation is associated with poorer prognosis, suggesting that SMARCA4 is an oncogene." (PMID 39697230, 2024). "Taken together, mutations in or near the bromodomain of SMARCA4 that prevent degradation of SMARCA4 are sufficient to allow for prostate cancer cell survival in the presence of mSWI/SNF ATPase degraders." (PMID 38557192, 2024). "Prostate cancer cell lines exposed to long-term treatment with high doses of a mSWI/SNF ATPase degrader developed SMARCA4 bromodomain mutations and ABCB1 (ATP binding cassette subfamily B member 1) overexpression as acquired mechanisms of resistance." (PMID 38557192, 2024). "Prostate cancer cell lines exposed to long-term treatment with high doses of a mSWI/SNF ATPase degrader developed SMARCA4 bromodomain mutations and ABCB1 overexpression as acquired mechanisms of resistance." (PMID 38464081, 2024). "In particular, increased expression of the SMARCA4 (Brg1) subunit was associated with the aggressive neuroendocrine phenotype of prostate cancer, marked by increased NE marker expression and shorter overall survival." (PMID 33572108, 2021). "In our study, we created numerous independent AU-15330-resistant prostate cancer lines and identified two classes of resistance mechanisms: one mechanism by which mutations occur in the drug binding site of SMARCA4 and another mechanism by which ABCB1 is overexpressed." (PMID 38557192, 2024). "Additionally, we characterized two independent potential resistance mechanisms to mSWI/SNF PROTAC degraders in prostate cancer models: one driven by mutations in the bromodomain of SMARCA4 and the other driven by ABCB1 elevation." (PMID 38557192, 2024). "We previously reported a highly selective PROTAC degrader targeting both mSWI/SNF ATPase subunits, SMARCA2 and SMARCA4, demonstrating remarkable therapeutic efficacy in various preclinical models of advanced prostate cancer through intravenous administration." (PMID 38557192, 2024). "There is a synthetic lethal relationship between SMARCA4 and the PTEN tumor suppressor in prostate cancer, rendering PTEN-deficient cells sensitive to SMARCA4 inhibition." (PMID 38390898, 2024). "Using the large prostate cancer cohort from TCGA, we found that SMARCA4 was significantly over-expressed." (PMID 33596994, 2021). "Previous work examining SMARCA4 expression in the TCGA prostate cancer cohort demonstrated that it is also up-regulated irrespective of Gleason score." (PMID 33596994, 2021). "In contrast, SMARCA4 has been reported as over expressed in cancers of the prostate, triple negative breast cancers and some leukaemias." (PMID 33596994, 2021). "Consistent with this, SMARCA4 expression was increased in a panel of both prostate cancer and transformed cell lines." (PMID 33596994, 2021). "Here, we examined the involvement of the SWI/SNF chromatin remodeller BRG1 and its associated encoding gene SMARCA4 in prostate cancer transcriptional deregulation." (PMID 33596994, 2021). "Examination of multiple prostate cancer cohorts has demonstrated elevated SMARCA4 expression or increased BRG1 protein levels." (PMID 33596994, 2021). "Of the several transcription factors identified, a few namely E2F1, MYC, YY1, CHD1 and SMARCA4 which have been shown to express in prostate cancer tissues are of particular interest." (PMID 25938433, 2015). "Similarly, SMARCA4 is required to maintain chromatin accessibility at lineage-specific enhancers to favor binding of transcription factors that drive prostate cancer cell proliferation." (PMID 38390898, 2024). "Notably, AR+FOXA1+ prostate cancer cells were more sensitive to these inhibitors than SMARCA4-null cancer cell lines." (PMID 34937944, 2022). "We have demonstrated that SMARCA4 mRNA over expression is a universal feature of prostate cancer." (PMID 33596994, 2021).
prostate carcinoma (continued). "Additionally, SMARCA4 can induce migration and invasion potential of prostate cancer cells." (PMID 36361605, 2022). "Under identical treatment conditions, AU-24118 demonstrated comparable degradation efficacy of SMARCA4 and PBRM1 to AU-15330 in VCaP prostate cancer cells." (PMID 38557192, 2024). "In this study, we utilized a PROTAC compound, AU-15330, that simultaneously degrades SMARCA4, SMARCA2, and PBRM1 and is toxic in enhancer-addicted prostate cancers." (PMID 37094128, 2023). "For example, it has recently been shown that androgen receptor (AR) and forkhead box A1 (FOXA1) expressing prostate cancer cells are sensitive to simultaneous degradation of BAF complex subunits SMARCA2, SMARCA4 and PBRM131." (PMID 36216795, 2022). "Recently, a new PROTAC degrader targeting SMARCA2 and SMARCA4, called AU-15330, was found to have great preferential cytotoxicity at low concentrations in AR/FOXA1-driven prostate cancer." (PMID 36361605, 2022). "Androgen receptor (AR)+ forkhead box A1 (FOXA1)+ prostate cancer cells are exquisitely sensitive to dual SMARCA2 and SMARCA4 degradation relative to normal and other cancer cell lines." (PMID 34937944, 2022). "We confirmed that SMARCA4 is over-expressed in prostate cancer irrespective of molecular subtype, and identified SMARCA4 was also over expressed in a panel of prostate cancer cell lines." (PMID 33596994, 2021). "We found that over expression of SMARCA4 commonly occurs in both the TCGA prostate cancer cohort, irrespective of tumour subtype, and in a panel of prostate cancer cell lines." (PMID 33596994, 2021). "Clinical studies of primary prostate tumours reported an overall increase in BRG1 protein by immunohistochemistry, and increased SMARCA4 gene expression has been reported in tumours from The Cancer Genome Atlas (TCGA) prostate cancer cohort compared to normal prostate tissue." (PMID 33596994, 2021). "Clinical datasets have shown that BRG1 protein levels are over-expressed in prostate cancer, in the absence of consistent significant deleterious genetic mutations evident in SMARCA4." (PMID 33596994, 2021). "Western blot analysis confirmed robust downregulation of direct targets (SMARCA2, SMARCA4, and PBRM1) and specific prostate cancer lineage proteins (AR, ERG, C-Myc, and PSA) after 5 d of AU-24118 treatment, whether administered alone or in combination with enzalutamide." (PMID 38557192, 2024). "Earlier research demonstrated that when AR-positive prostate cancer cells were treated with a proteolysis-targeting chimera (PROTAC) that degraded the ATPase subunits of the SWI/SNF chromatin remodeling complex (namely SMARCA2 and SMARCA4), it led to physical compaction of enhancer elements." (PMID 38586029, 2024). "We next examined both BRG1 protein and SMARCA4 gene expression levels in normal prostate epithelial cells (PrEC) and compared to LNCaP (lymph node metastasis), an androgen-sensitive prostate cancer cell line, as well as PC3 (bone metastasis), an androgen-insensitive prostate cancer cell line." (PMID 33596994, 2021). "Therefore, we conclude that at the mRNA level, SMARCA4 is universally over-expressed in prostate cancer, regardless of clinical grade or molecular subtype." (PMID 33596994, 2021). "Thus, it is possible that SMARCA4 overexpression may be necessary, but not sufficient, to promote an aggressive phenotype in prostate cancer cells." (PMID 33144576, 2020). "Although specific trials for bone metastatic breast or prostate cancers are currently absent, the expanding array of SWI/SNF-targeting agents, including BRD9 degraders and SMARCA4/2 inhibitors, provides a basis for future translational research in this domain." (PMID 40872531, 2025). "This implies that SMARCA4, rather than SMARCA2 or PBRM1, may be the critical target to perturb in the context of prostate cancer therapy." (PMID 38557192, 2024).